MIR203A (microRNA 203a)
Synonyms: hsa-mir-203; MIR203; MIRN203; hsa-mir-203a; miR-203; miRNA203; mir-203a
Gene: MicroRNA gene on chromosome 14 (104,117,405 to 104,117,514, forward strand). Ensembl gene ENSG00000207568.
Gene Ontology:
Biological process: miRNA-mediated post-transcriptional gene silencing
Cellular component: RISC complex
Diseases named in the same sentence as MIR203A in open-access papers:
MIR203A is named in the same sentence as 11 diseases in open-access papers, as found by Europe PMC text mining. Sharing a sentence is not in itself a finding about the gene and the disease. The quoted sentences say what the papers report.
ovarian tumors (1 paper, 2022). "Thus, hypermethylation of the MIR203A gene may be a very useful biomarker of metastatic primary ovarian tumors." (PMID 35163224, 2022).
MIR203A also shares sentences with these, for which no sentence is quoted: tumor (2 papers); breast carcinoma (1); cancer (1); Cerebral ischemia (1); hematological cancers (1); metastatic tumors (1); neuroblastoma (1); pancreatic adenocarcinoma (1); periodontitis (1); triple-negative breast carcinoma (1).